LGALS2 (galectin 2)
Diseases named in the same sentence as LGALS2 in open-access papers (continued):
Sharing a sentence is not in itself a finding about the gene and the disease.
coronary stenosis (1 paper, 2016). Narrowing of the coronary artery lumen diameter. "Studies even found the TT genotype, which leads to lower levels of galectin-2, to be associated with more severe coronary stenosis and higher levels of C-reactive protein." (PMID 27903268, 2016).
COVID-19 (1 paper, 2025). A disease caused by infection with severe acute respiratory syndrome coronavirus 2. "In particular, the persistent upregulation of the LGALS2 gene from the moderate to severe and ICU stages suggests its potential key role in COVID-19 pathogenesis." (PMID 40444276, 2025).
limb ischemia (1 paper, 2015). A ischemia that involves the limb. "The same researchers also found that galectin-2 was able to inhibit collateral circulation in a mouse model of limb ischemia." (PMID 25959001, 2015).
liver cancer (1 paper, 2025). An epithelial or non-epithelial malignant neoplasm that arises from the liver. "Discovered in 1992 within the cDNA library of human liver cancer cell HepG2, LGALS2 is positioned on the opposite strand of the same chromosome as LGALS1, approximately 50 kb away." (PMID 40134029, 2025).
rheumatoid arthritis (1 paper, 2022). A chronic, systemic autoimmune disorder characterized by inflammation in the synovial membranes and articular surfaces. "The presence of galectin-2 SNP in intron 1 (3279C/T) was suggested to be a marker of high risk of cardiovascular events in rheumatoid arthritis." (PMID 36613785, 2022). "Three different genotype groups of galectin-2 SNPs (CC, CT and TT genotypes) in intron 1 have been reported to be associated with high diastolic blood pressure in patients with rheumatoid arthritis." (PMID 36613785, 2022).
viral infection (1 paper, 2023). "Genes down-regulated in the pro-inflammatory monocytes of ACLF patients included FOS, CCL3 and LGALS2, which are mainly associated with resistance to viral infection, promotion of apoptosis, and immunosuppression." (PMID 36626090, 2023).
tumor (28 papers, 2018 to 2025). "Lastly, although the results of this study supported the involvement of LGALS2 in tumor immune regulation and immunotherapy, the underlying molecular mechanism needs further investigation." (PMID 37838802, 2023). "The result that high LGALS2 expression was associated with reduced occurrence of clinical tumor therapy resistance was even more intriguing for us." (PMID 37838802, 2023). "Five genes were identified as potential regulators of immune surveillance in all screening settings, among which galectin 2 (Lgals2) induced the increased number of tumor-associated macrophages and resulted in the immunosuppressive microenvironment." (PMID 38162677, 2023). "Lgals2 was pulled out from the screen as a promoter of the immune escape mechanism consisting of an increase in tumour-associated macrophages and their switch to the prooncogenic phenotype M2-like." (PMID 37686639, 2023). "Furthermore, these results indicated that LGALS2 expression was associated with tumor immunotherapy and could serve as a biomarker for response to immunotherapy." (PMID 37838802, 2023). "Supporting this, the gene LGALS2, which encodes Galectin-2, has been linked to greater infiltration of TIM-3+ CTLs within the tumor microenvironment, suggesting a more extensive role of galectin in modulating TIM-3 signaling." (PMID 41550427, 2025). "Conversely, exosomes isolated from OC cells treated with naphthoquinone shikonin (SK), which has anti-tumor effects, were found to inhibit M2 polarization of macrophages by blocking β-catenin activation mediated by exosomal galectin-2 (LGALS2)." (PMID 39334866, 2024). "Next, we explored the unique function of WDR45B+ TAMs compared to the other TAMs, and found upregulation of several known tumor-promoting genes, such as LGALS2 and GPR183." (PMID 38414027, 2024). "Intriguingly, some of the genes associated with a better survival are associated with different immune populations, such as MFGN and LGALS2, suggesting that these results reflect the anti-tumor immune responses." (PMID 38384845, 2024). "Here, we found that LGALS2 promoter methylation levels were high in the tumor groups (P < 0.001) and were closely related to the tumor subtypes and patient age (P < 0.05)." (PMID 37838802, 2023). "Based on our observations, the overexpression of galectin-2 can play a tumour-suppressive role in the H-RasG12V-activated HCC cells, where H-Ras also plays an important role in HCC oncogenesis." (PMID 37371482, 2023). "Injection of 4 T1 cells into the mouse mammary fat pad, followed by injection of therapeutic antibody against galectin-2 function, arrested tumor growth and successfully reversed the immunosuppressive phenotype." (PMID 36873388, 2023). "In contrast, SNX3 and LGALS2 are antitumor factors that inhibit tumor cell growth and metastasis, which is consistent with the phenotype of type I conventional DCs." (PMID 37533434, 2023). "Patients with metastasis were shown to have even higher amounts of circulating galectin-2 than those with only localised tumours." (PMID 36613785, 2022). "As for CRISPR technology, genome-wide CRISPR screens have served for the identification of oxidative stress-responsive genes in CRC such as Galectin-2 (Gal2) which has a tumor-suppressive role in this cancer." (PMID 34680186, 2021). "Several of the GRGs and GRPs commonly correlated with survival in different tumor types are actually associated with specific cells in the stromal compartment (as MFNG in all immune cells, LGALS2 in myeloid cells, ST6GAL1 in B and plasma cells and CHPF and ST3GAL4 for fibroblasts)." (PMID 38384845, 2024). "The TCGA database was used to analyze the expression of LGALS2 in various normal and tumor tissues." (PMID 37838802, 2023).
tumor (continued). "A significant increase in promoter methylation of LGALS2 was observed in tumor samples as compared to the normal group (P < 0.0001), and this was also significantly associated with the tumor type and patient age, which were inversely correlated with LGALS2 mRNA expression level." (PMID 37838802, 2023). "Besides, we observed that LGALS2 expression gradually decreased with tumor progression in DLBCL and that high LGALS2 expression predicted a better prognosis for DLBCL patients." (PMID 36389761, 2022). "With respect to other human galectins, including galectin-2, -10, -12, -13, -14 and -16, our knowledge of these galectins remains rather fragmentary regarding their intracellular roles in cancer, or even their role once released into the tumor microenvironment for that matter." (PMID 37753083, 2023). "Therefore, it would be necessary to investigate further whether galectin-2 blockade may inhibit several routes of galectin-2-mediated malignancy, including tumor growth, immunosuppression, and thromboinflammation." (PMID 36873388, 2023). "The results showed that LGALS2 expression was statistically significant among 11 groups including BLCA (P < 0.01), and was much lower in tumor groups, especially in BRCA (P < 0.001)." (PMID 37838802, 2023). "The HPA database showed that proteins (CD177, LGALS2, TMC8, and VWA5A) were significantly dysregulated in tumor tissue relative to normal samples." (PMID 37528394, 2023). "Binding of galectin-2 to the oncofetal Thomsen-Friedenreich antigen Galβ1,3GalNAcα- (TF antigen) on the mucin protein MUC1 of tumour cells enhanced cancer cell adhesion to the vascular endothelium." (PMID 36613785, 2022). "HEPACAM2, ITLN1, LGALS2, MUC12, and NXPE1 presented a sequentially descending trend in expression with tumor progression." (PMID 29659199, 2018). "Concerning galectin-2, a recent study demonstrated that it plays a crucial role in TNBC by contributing to the formation of an immunosuppressive microenvironment, possibly following the release of its form extracellular by the tumor cell." (PMID 37753083, 2023). "However, in triple-negative breast cancer, galectin-2 was found to act on immunosuppression in vivo to promote tumour growth but not to act on cancer cells." (PMID 37371482, 2023). "Likewise, Lgals2 overexpression and inhibition via CRISPR/Cas9 edition increased or reduced in vivo tumour growth, respectively, suggesting that Lgals2 could be a promising target for immunotherapy." (PMID 37686639, 2023).
cancer (13 papers, 2016 to 2025). A tumor composed of atypical neoplastic, often pleomorphic cells that invade other tissues. "Several studies have reported an association of galectin-2 expression with cancer prognosis in breast and colon cancer patients." (PMID 36613785, 2022). "Therefore, LGALS2 expressed levels might be associated with the increased sensitivity of cancer cells to clinical drugs and longer survival of cancer patients." (PMID 37838802, 2023). "LGALS2 is also closely related to immunotherapy response and plays an active role in cancer therapy." (PMID 37838802, 2023). "Although several studies pointed out the pro-inflammatory and pro-angiogenic functions of galectin-2, experimental evidence is still missing to conclude the exact role of galectin-2 during cancer progression and metastasis." (PMID 36873388, 2023). "Although with different binding affinities, other galectin members also recognize TF antigen and several of them, such as galectin-1, galectin-2, -4, and -8, are shown to also have elevated levels in the circulation of cancer patients." (PMID 27066458, 2016). "The results showed that APOE, CTSD, LGALS2, and TMEM176B expression in normal tissues was significantly higher than that in cancer tissues (P < 0.01)." (PMID 34873574, 2021). "In support of this, exogenous introduction of recombinant galectin-2, -4, or -8 at broadly pathological concentrations observed in cancer showed to induce changes of MUC1 cell surface localization and increase of cancer cell adhesion to endothelial monolayers in cell culture." (PMID 27066458, 2016).
infection (3 papers, 2019 to 2025). The state of being infected such as from the introduction of a foreign agent such as serum, vaccine, antigenic substance or organism. "alter host LGALS2 expression after infection and the exact role of galectin-2 in host response during IPA." (PMID 35205926, 2022).
cardiovascular disease (2 papers, 2016 to 2022). "For example, LGALS2 was originally studied for its function in cardiovascular diseases as an inflammatory factor." (PMID 36389761, 2022). "Thus while prior studies suggest that galectin-2 may play a role in cardiovascular disease, potentially by modulating both pro-inflammatory and anti-inflammatory cytokines, the mechanism and direction of association remain to be determined." (PMID 27903268, 2016).
dermatosis (2 papers, 2023 to 2025). "Additionally, we have demonstrated a potential role of galectin-2 and -12 in this dermatosis." (PMID 41226378, 2025).
metabolic disorder (2 papers, 2021 to 2023). "Association between LGALS1 (gal-1 gene) and GDM complicated pregnancy, LGALS2 (gal-2 gene) and fasting insulin and glucose has been reported, however, further studies are necessary to understand their roles in the development of metabolic disorder during gestation." (PMID 35046934, 2021).
LGALS2 also shares sentences with these, for which no sentence is quoted: preeclampsia (5 papers); atherosclerosis (3); colon carcinoma (3); colorectal cancer (3); endometriosis (2); lymph node metastasis (2); lymphoma (2); alcoholism (1); Anxiety (1); aortic stenosis (1); atopic dermatitis (1); autoimmune disease (1); Chronic colitis (1); colorectal tumors (1); contact allergic dermatitis (1); depression (1); diabetes (1); egg allergy (1); escherichia coli infection (1); gastrointestinal stromal tumor (1); Helicobacter infection (1); ischemia (1); neutropenia (1); ovarian carcinoma (1); psoriasis (1); respiratory arrest (1); uveal melanoma (1).